TBC1D9 (TBC1 domain family member 9)
Description:
May act as a GTPase-activating protein for Rab family protein(s).
Synonyms: KIAA0882; MDR1; GRAMD9
Tractability: PROTAC: ubiquitination databases record sites on it.
Gene: Protein-coding gene on chromosome 4 (140,620,782 to 140,756,982, reverse strand). Ensembl gene ENSG00000109436.
Subcellular location (Human Protein Atlas): Cytosol
Gene Ontology:
Molecular function: protein binding; GTPase activator activity; calcium ion binding
Biological process: system process
Genetic constraint (gnomAD): Loss-of-function variants: 48 observed, 102.66 expected, observed/expected ratio (o/e) 0.47, 90% interval 0.37 to 0.6. The upper end of that interval is the gene's LOEUF score, 0.6, which puts it in group 2 of 6, group 1 being the genes least tolerant of losing a copy. Missense variants: 943 observed, 1,233.6 expected, observed/expected ratio (o/e) 0.76, 90% interval 0.72 to 0.81. Synonymous variants: 460 observed, 464.01 expected, observed/expected ratio (o/e) 0.99, 90% interval 0.92 to 1.07.
Homologues: Orthologues: chimpanzee TBC1D9 (100% identical), macaque TBC1D9 (99% identical), rabbit TBC1D9 (98% identical), dog TBC1D9 (97% identical), pig TBC1D9 (97% identical), mouse Tbc1d9 (96% identical), rat Tbc1d9 (95% identical), guinea pig TBC1D9 (93% identical), tropical clawed frog tbc1d9 (84% identical), zebrafish tbc1d9 (79% identical). Paralogues in human: TBC1D9B (63% identical), TBC1D8B (46% identical), TBC1D8 (46% identical), SGSM3 (15% identical), RABGAP1L (12% identical), TBCK (12% identical), RABGAP1 (11% identical), TBC1D1 (11% identical), TBC1D2B (11% identical), TBC1D4 (11% identical), TBC1D2 (11% identical), TBC1D10A (10% identical), and 33 more.
Diseases named in the same sentence as TBC1D9 in open-access papers:
TBC1D9 is named in the same sentence as 15 diseases in open-access papers, as found by Europe PMC text mining. Sharing a sentence is not in itself a finding about the gene and the disease. The quoted sentences say what the papers report.
breast carcinoma (10 papers, 2013 to 2024). "Notably, the transcripts occupying the block associated with PAM50 subtype include CA12, GABRP, NAT1 and TBC1D9, which have been previously proposed as predictor genes for breast cancer mortality, recurrence and drug response." (PMID 35758795, 2022). "Expression of TBC1D9, a Rab GTPase accelerating protein, is highly correlated with ERα and Gata3 expression in human breast cancers." (PMID 29262572, 2017). "THSD4 and TBC1D9 are two factors that drive TNBC, and their expression is also linked to the epithelial–mesenchymal transition (EMT), metastatic dissemination, and the plasticity of breast cancer cells." (PMID 38020889, 2023). "TBC1D9 is a gene implicated as a long-term survival gene in breast cancer 108, its expression can differentiate TNBC (low) from non-TNBC (high) breast cancer samples, and overexpression leads to better prognosis 109, which is similar to our study." (PMID 35664067, 2022). "While the role of TBC1D9 is unknown in breast cancer, there is evidence that alterations in RAB GTPases play a role in progression of certain carcinomas." (PMID 23819905, 2013). "Expression of TBC1D9 and CEACAM6 was higher in GATA3 mutant MCF-7 cells, GATA3 mutant CAMA1 cells, and primary GATA3 mutant breast cancer cells, whereas expression of PPT1, CYBRD1, HOXC13, and AFF3 was higher in GATA3 wild type cells." (PMID 29262572, 2017). "Multivariable analyses using the LASSO revealed that expression of PGR, ESR1, NAT1, GABRP, TBC1D9, SLC39A6 and LRBA of the 32 gene candidates was collectively the most important predictors for both breast cancer mortality and recurrence." (PMID 23819905, 2013). "This cohort contained a subset of genes that could be considered potential biomarkers for breast cancer progression, including FOXA1, MLPH, ESR1, AR, GATA3, TFF1, THSD4, and TBC1D9." (PMID 38020889, 2023). "A similar result was obtained when using a six-gene (AGR2, SLC44A4, TBC1D9, FOXA1, GATA3, and CA12) breast cancer steroid response module (Kruskal-Wallis p = 0.01 across all patients, p = 0.94 in HRDetect-high patients, and p = 0.02 in HRDetect-low/intermediate patients)." (PMID 33568222, 2021).
autoimmune disease (2 papers, 2020 to 2022). A disorder resulting from loss of function or tissue destruction of an organ or multiple organs, arising from humoral or cellular immune responses of the individual to their own tissue constituents. "TBC1D9 appears to be a specific regulator in response to Ca2+ signaling and could regulate TBK1 activation associated with autoimmune disease." (PMID 35359935, 2022).
colorectal cancer (2 papers, 2024 to 2025). A primary or metastatic malignant neoplasm that affects the colon or rectum. "Regardless of heterogeneity with respect to non‐TNBC patients, all of them had a downregulation of the TBC1D9 gene; and up‐regulation of TBC1D9 expression inhibited migration in colorectal cancer." (PMID 40384436, 2025).
depression (1 paper, 2020). "In our biomarker analysis, expression of GAD1, NFIB, and TBC1D9 showed associations with response status, remission status, and improvement in depression scale, respectively, but not with treatment resistance." (PMID 32612257, 2020). "Results from the STAR*D study showed a marginal association of treatment-resistant depression with NFIB (p = 0.068) but not with GAD1 (p = 0.23) and TBC1D9 (p = 0.27)." (PMID 32612257, 2020).
mantle cell lymphoma (1 paper, 2021). Mantle cell lymphoma is a rare form of malignant non-Hodgkin lymphoma affecting B lymphocytes in the lymph nodes in a region called the ``mantle zone''. "TBC1D9 (TBC1 domain family member 9) encodes a potential GTPase and was found to be overexpressed in mantle cell lymphoma." (PMID 33830993, 2021).
melanoma (1 paper, 2023). A malignant, usually aggressive tumor composed of atypical, neoplastic melanocytes. "TBC1D9 (another member of the family and a potential GAP) is a component gene of Overlap36, indicating the importance of this family in melanoma immune evasion." (PMID 36588164, 2023).
meningioma (1 paper, 2014). A generally slow growing tumor attached to the dura mater. "BTBD3, LOC339535, and TBC1D9 genes were present in both lists, and thus are potentially important in meningioma pathogenesis." (PMID 25003081, 2014).
cancer (7 papers, 2013 to 2025). A tumor composed of atypical neoplastic, often pleomorphic cells that invade other tissues. "This clinical data demonstrates a positive correlation to our mouse stress studies, linking stress to DNA methylated genes Cdh10 and Tbc1d9, related to cancer prognosis and survival." (PMID 35664067, 2022). "This shows that CDH10 and TBC1D9 are important genes in cancer and stress." (PMID 35664067, 2022). "TBC1D9 overexpression was also found increased in carcinomas of males compared to those of females and may therefore represent a novel molecular target for development of gender-specific therapeutics and companion diagnostics." (PMID 33535487, 2021). "For instance, TBC1D9 has been described as over expressed in cancer patients." (PMID 28241739, 2017).
tumor (7 papers, 2013 to 2024). "We observed that low expression of TBC1D9 was associated with the high-grade tumor (p < 0.0001)." (PMID 34298771, 2021). "The association of low expression of TBC1D9 with large tumor size observed in all BC patients may explain the positive correlation of the low expression of TBC1D9 with advanced stage BC in this population of patients." (PMID 34298771, 2021). "Taken together, these data suggest an important role of TBC1D9 as a modulator of BC migration and tumor growth." (PMID 34298771, 2021). "The analysis of the BC dataset from the GENT2 database showed a similar difference in the TBC1D9 RNA expression in different BC tumor grades." (PMID 34298771, 2021). "As the 3D spheroid formation assay indicated that TBC1D9 has an inhibitory effect on tumor growth, this prompted us to further verify this finding in an in vivo system using a CAM assay." (PMID 34298771, 2021). "The interesting effect of TBC1D9 on migration and tumor growth in luminal BC and TNBC led us to investigate the signaling involved in mediating these effects and how the signaling in BC with HER2 expression differs from other BC subtypes." (PMID 34298771, 2021). "Our results suggest that TBC1D9 expression might limit tumor aggressiveness and that it has a differential expression in TNBC vs. non-TNBC tumors." (PMID 34298771, 2021). "Furthermore, we identified TBC1D9 as an important regulator of migration and tumor growth in BC." (PMID 34298771, 2021). "Among the 991 BC tumor samples, GATA3 had the highest frequency of somatic SNVs, accounting for 13%; followed by FOXA1, accounting for 3%; AGR2, CA12, CEP55, CDC20, TBC1D9, and MELK had very few somatic SNVs." (PMID 39440050, 2024). "Protein–protein interaction analysis by affinity purification mass spectrometry (AP-MS) and proximity biotinylation (BioID) experiments identified a role for TBC1D9 in maintaining cellular integrity, whereas MFGE8 would be involved in various tumor survival processes." (PMID 32591639, 2020). "For example, we found that ATAD1, TBC1D9, and TNNC2 expression are all mediated by transcription factors ACTRT2, MMP23B, and TP73 and methylation sites around MMP23B and TP73; these transcription factors have known functions in tumor suppression or proliferation." (PMID 33684137, 2021). "In the present study, analysis of TBC1D9 expression in TNBC (n = 58) and non-TNBC (n = 25) patient tumor samples validated that TBC1D9 expression can differentiate TNBC (low) from non-TNBC (high) samples and that expression of TBC1D9 was inversely correlated with grade and proliferative index." (PMID 34298771, 2021). "However, it seems that TBC1D9 behaves differently in HER2-positive BC, where it might act as a tumor promoter in the absence of ER." (PMID 34298771, 2021).
infection (4 papers, 2020 to 2025). The state of being infected such as from the introduction of a foreign agent such as serum, vaccine, antigenic substance or organism. "To determine if TBC1D9’s role during hypervirulent infection extends beyond IL-6, we infected epithelial cells with GAS SSI-1 (M3) and measured the expression of IFN-β, TNF-α, IL-1β, and IL-8." (PMID 41306588, 2025). "22.7% of WT GAS-infected cells showed endogenous TBC1D9-positive bacteria, which were rarely observed followingΔslo infection." (PMID 32034138, 2020). "Across these infections, IL-6 mRNA expression and protein secretion were consistently reduced in TBC1D9-KO cells compared to WT controls (p < 0.05), indicating that TBC1D9 regulates IL-6 responses to various bacterial pathogens." (PMID 41306588, 2025). "TBC1D9 was also recently found to be involved in a Ca2+-dependent cellular response to infection." (PMID 33830993, 2021). "Moreover, TBC1D9 recruitment increased over time after infection, with the kinetics revealing that TBC1D9 localization to GAS was similar to that of ubiquitin and LC3." (PMID 32034138, 2020). "To examine if TBC1D9 is also required for the recruitment of ULK1 to the invading GAS, we observed the ULK1 localization during infection." (PMID 32034138, 2020). "Proteomics identified Rab29 as a TBC1D9 partner; co-immunoprecipitation showed preferential interaction with GTP-dependent Rab29, and the two proteins co-localized following stimulation and infection." (PMID 41306588, 2025). "To determine whether TBC1D9 targets cytosolic GAS, we detected the localization of endogenous TBC1D9 during GAS WT or ∆slo infection." (PMID 32034138, 2020). "To confirm whether TBC1D9 is involved in autophagosome formation, we examined the conversion of LC3-I to LC3-II during infection." (PMID 32034138, 2020). "We previously reported that endosome-resident RAB35 and TBC1D9 recruit NDP52 for triggering xenophagy, and thus a highly sophisticated mechanism may exist for regulating autophagy receptors in response to infection." (PMID 33425778, 2020). "We further confirmed that the increase in cytosolic Ca2+ during infection is not affected by knockout of STING, TBK1, and TBC1D9, suggesting that TBK1 activation is not required for Ca2+ elevation." (PMID 32034138, 2020).
bacterial infection (2 papers, 2020 to 2025). "Given that TBC1D9 selectively regulates IL-6 expression in epithelial cells during cytosolic DNA sensing and bacterial infection, we then aimed to see if this regulatory pathway is also relevant in human disease." (PMID 41306588, 2025). "Together, these findings identify TBC1D9 as an essential and selective regulator of IL-6 expression in response to both cytosolic DNA sensing and diverse bacterial infection." (PMID 41306588, 2025). "Our study identifies TBC1D9 as a selective regulator of IL-6 expression in epithelial cells during innate immune responses to cytosolic DNA and bacterial infections." (PMID 41306588, 2025). "The TBC1D9-Rab29 axis defines a regulatory mechanism and a potential therapeutic target for reducing excessive inflammation in bacterial infections and inflammatory diseases." (PMID 41306588, 2025). "Together, our data support a model in which the TBC1D9 regulates IL-6 expression through a Rab29-mediated pathway, balancing immune responses during bacterial infection." (PMID 41306588, 2025). "Here, we show that bacterial infection increases Ca2+ levels to activate TBK1 for xenophagy via the Ca2+-binding protein TBC1 domain family member 9 (TBC1D9)." (PMID 32034138, 2020). "Together, TBC1D9 enhances IL-6 expression in epithelial cells during cytosolic DNA sensing and various bacterial infections, sustaining homeostatic NF-κB activity but not stimulus-induced activation." (PMID 41306588, 2025).
TBC1D9 also shares sentences with these, for which no sentence is quoted: gastric cancer (1 paper); infectious disease (1); lung carcinoma (1); sarcoma (1).